MTHFD2 (methylenetetrahydrofolate dehydrogenase (NADP+ dependent) 2, methenyltetrahydrofolate cyclohydrolase)
Description:
Although its dehydrogenase activity is NAD-specific, it can also utilize NADP at a reduced efficiency.
Synonyms: NMDMC
Tractability: Small molecule: a structure with a bound ligand is known; a high-quality ligand is known. PROTAC: UniProt records ubiquitination sites on it; ubiquitination databases record sites on it; its protein half-life has been measured; a small molecule that binds it is known.
Target class: Enzyme; Oxidoreductase
Chemical probes: TH9619 (high quality)
Gene: Protein-coding gene on chromosome 2 (74,186,172 to 74,217,565, forward strand). Ensembl gene ENSG00000065911.
Subcellular location: Mitochondrion
Subcellular location (Human Protein Atlas): Mitochondria
Pathways (Reactome):
Metabolism: Metabolism of folate and pterines
Gene Ontology:
Molecular function: magnesium ion binding; methenyltetrahydrofolate cyclohydrolase activity; methylenetetrahydrofolate dehydrogenase (NAD+) activity; methylenetetrahydrofolate dehydrogenase (NADP+) activity; phosphate ion binding; protein binding; catalytic activity
Biological process: tetrahydrofolate metabolic process; folic acid metabolic process; tetrahydrofolate interconversion; formate biosynthetic process
Cellular component: extracellular region; mitochondrion; mitochondrial matrix
Genetic constraint (gnomAD): Loss-of-function variants: 20 observed, 29.54 expected, observed/expected ratio (o/e) 0.68, 90% interval 0.47 to 0.98. The upper end of that interval is the gene's LOEUF score, 0.98, which puts it in group 4 of 6, group 1 being the genes least tolerant of losing a copy. Missense variants: 334 observed, 402.17 expected, observed/expected ratio (o/e) 0.83, 90% interval 0.76 to 0.91. Synonymous variants: 154 observed, 148.03 expected, observed/expected ratio (o/e) 1.04, 90% interval 0.91 to 1.19.
Homologues: Orthologues: chimpanzee MTHFD2 (99% identical), macaque MTHFD2 (97% identical), guinea pig MTHFD2 (93% identical), dog MTHFD2 (92% identical), mouse Mthfd2 (92% identical), pig MTHFD2 (90% identical), rat Mthfd2 (90% identical), Drosophila melanogaster pug (40% identical), Caenorhabditis elegans dao-3 (32% identical), Caenorhabditis elegans K07E3.4 (3% identical). Paralogues in human: MTHFD2L (64% identical), MTHFD1 (37% identical), MTHFD1L (23% identical).
Diseases named in the same sentence as MTHFD2 in open-access papers:
MTHFD2 is named in the same sentence as 105 diseases in open-access papers, as found by Europe PMC text mining. Sharing a sentence is not in itself a finding about the gene and the disease. The quoted sentences say what the papers report.
breast carcinoma (41 papers, 2013 to 2025). "Among other types of cancers, MTHFD2 has been identified as a risk gene in ovarian, colorectal, lung, and breast cancers." (PMID 38506898, 2024). "Studies also found that the high expression of MTHFD2 is correlated with the migration and invasiveness of breast cancer cells and is associated with a poor prognosis in breast cancer." (PMID 39595564, 2024). "In breast cancer cells, MTHFD2 depletion caused a weaker and deformed vimentin network, indicating the impairment of cell motility." (PMID 32411609, 2020). "For instance, loss of MTHFD2 led to glycine auxotrophs (i.e., a reliance on exogenous glycine) in mammalian fibroblasts, breast cancer, and AML." (PMID 32411609, 2020). "Increased MTHFD2 expression is associated with acute myeloid leukemia, breast cancer, lung cancer, and liver cancer, and MTHFD2 is considered a novel target for anticancer therapy." (PMID 29225823, 2017). "Bioinformatic analysis of gene expression data across cancers indicated overexpression of EPHB4 and MTHFD2 in breast cancer and high expression associated with poor clinical characteristics." (PMID 23295955, 2013). "Moreover, suppression of MTHFD2 in MCF-7 breast cancer cells caused prominent metabolic remodeling, such as greater vulnerability to exogenous folate depletion, enhanced glycolytic flux, and increased glutamine consumption." (PMID 32411609, 2020). "High MTHFD2 expression associated with poor clinical characteristics in breast cancer and functional characterization indicated that this enzyme is a putative regulator of breast cancer cell migration and invasion." (PMID 23295955, 2013). "Our results show that MTHFD2 is overexpressed in breast cancer, associates with poor clinical characteristics and promotes cellular features connected with metastatic disease, thus implicating MTHFD2 as a potential drug target to block breast cancer cell migration and invasion." (PMID 23295955, 2013). "Interestingly, MTHFD2 had been previously associated as one of potential cancer biomarkers in quantitative proteomic study of cultured breast cells from normal breast tissue, primary breast cancer and metastatic breast cancer derived from the same patient." (PMID 23295955, 2013). "Suppression of MTHFD2 in breast cancer cells increased the flux of glycolysis and glutamine consumption, as well as their sensitivity to glycine and folate depletion." (PMID 40604332, 2024). "Based on data analysis related to breast cancer and animal experiments, this study revealed that downregulation of MTHFD2 can promote cellular senescence, thereby accelerating tumor growth." (PMID 39668825, 2024). "Enhanced expression of mitochondrial folate cycle enzymes such as SHMT2, MTHFD2, and MTHFD1L was also detected in cancer cell lines using metabolic profiling, and this was associated with higher mortality in breast cancer patients." (PMID 38698089, 2024). "As expected for an oncogene candidate, MTHFD2 levels was found increased in other types of cancer, such as colorectal cancer, urothelial carcinoma, breast cancer, esophageal squamous cell carcinoma, as well as lung adenocarcinoma." (PMID 38422037, 2024). "On subtype analysis of breast cancer based on TCGA and GEO databases, MTHFD2 expression was found to be higher in the basal (TNBC) and human epidermal receptor 2-amplification subtypes than in the luminal subtype." (PMID 36726381, 2023). "To ensure that the described mechanism is also consistent across a broader panel of cell lines, we aimed to verify the effects of TH9619 treatment in breast cancer cell lines with different expression levels of MTHFD2." (PMID 37012496, 2023). "A nomogram model was subsequently constructed to estimate the survival probability of breast cancer patients by combining multiple clinical characteristics and MTHFD2 expression levels." (PMID 36726381, 2023).
breast carcinoma (continued). "Survival curves obtained from various databases demonstrated that higher MTHFD2 expression conferred poorer prognosis with both breast cancer and TNBC." (PMID 36726381, 2023). "The correlation between the expression of MTHFD2 and multiple immune checkpoint molecules in breast cancer was also evaluated in this study." (PMID 36726381, 2023). "RT-qPCR and Western blot assays were performed to detect MTHFD2 mRNA and protein expression levels in multiple human breast cancer cell lines (MDA-MB-468, MDA-MB-231, MCF7, SKBR3, and BT474) and the normal human breast cell line (MCF10A)." (PMID 36726381, 2023). "Based on data from TCGA and GEO databases, we found mRNA expression levels of MTHFD2 to be prominently up-regulated in breast cancer samples than in normal tissue samples." (PMID 36726381, 2023). "In breast cancer, miR-9 exerts anti-proliferative, anti-invasive and proapoptotic effects by targeting MTHFD2." (PMID 37147729, 2023). "MTHFD2, a folate‐coupled mitochondrial metabolic enzyme, is upregulated in many types of rapidly proliferating cancers such as breast cancer and colorectal cancer." (PMID 37480214, 2023). "We then explored genomic alterations and biologically relevant functions of MTHFD2 in breast cancer." (PMID 36726381, 2023). "The deletion of MTHFD2 copy numbers was the most critical factor affecting immune infiltration in breast cancer." (PMID 36726381, 2023). "In vitro, RT-qPCR and western blot assays were utilized to identify the MTHFD2 expression and the knockdown effects in breast cancer." (PMID 36726381, 2023). "The underlying biological function and tumor-related signaling pathways of MTHFD2 in breast cancer were predicted by GSEA." (PMID 36726381, 2023). "MTHFD2 is overexpressed in breast cancer, colorectal cancer, liver cancer, hepatocellular carcinoma, and bladder cancer too7–9." (PMID 37872243, 2023). "TNBC cells (MDA-MB-231 and MDA-MB-468) demonstrated higher MTHFD2 expression than cells of other breast cancer subtypes." (PMID 36726381, 2023). "Methylenetetrahydrofolate dehydrogenase 2 (MTHFD2) is a promising druggable target and is overexpressed in cancerous cells, like, breast cancer." (PMID 37872243, 2023). "In this context, MTHFD2 also regulates apoptosis-related genes, including Bcl2 and Bax, to affect apoptosis in breast cancer." (PMID 36726381, 2023). "On employing the ESTIMATE algorithm to estimate the impact of MTHFD2 on the TME of breast cancer, the group with high MTHFD2 expression was found to have lower stroma and ESTIMATE scores (but not immune scores)." (PMID 36726381, 2023). "The enrichment analysis results identified the MAPK, WNT, PI3K-AKT, JAK-STAT, and NF-κB signaling pathways to be potentially involved in the regulation of MTHFD2-induced proliferation of breast cancer." (PMID 36726381, 2023). "In breast cancer, MTHFD2 was reported to activate the AKT signaling pathway to promote tumorigenesis." (PMID 35581573, 2022). "Markedly elevated expression of MTHFD2 was identified in many cancers and correlates with poor survival in breast cancer patients." (PMID 35135596, 2022). "In particular, the authors found that the MTHFD2 RNA and protein were markedly elevated in many cancers, and these increased levels are correlated with poor survival in breast cancer." (PMID 35328637, 2022). "Through microarray profiling, MTHFD2 is identified as a target of miR‐9 which inhibits cell proliferation in breast cancer." (PMID 34121323, 2021). "MTHFD2 expression is markedly elevated in many cancers and correlates with poor survival in breast cancer." (PMID 33468252, 2021). "Consistently, MTHFD2 has also been reported to affect cancer cell migration and invasion abilities by modulating vimentin expression in breast cancer and renal cell carcinoma." (PMID 34121323, 2021). "In breast cancer, MTHFD2 is identified to regulate the migration and invasion abilities of tumour cells." (PMID 34121323, 2021).
breast carcinoma (continued). "Hypoxia-inducible factors (HIF) has reported to regulate expression of genes encoding PHGDH and five downstream enzymes including MTHFD2 and SHMT2 in the serine synthesis pathway and mitochondrial one-carbon cycle in breast cancer stem cells." (PMID 33468252, 2021). "In 2014, a meta-analysis study of 19 types of human cancers showed that MTHFD2 was overexpressed in various tumors, including breast cancer, colon cancer, and liver cancer." (PMID 32411609, 2020). "Transcriptome profiling in breast cancer cells identified MTHFD2 as a target gene of miR-9 that affected cell proliferation and induced apoptosis." (PMID 32411609, 2020). "RNA interference targeting MTHFD2 had been shown to suppress cancer cell malignant features and cause cell death in various cancers, including AML, CRC, HCC, RCC, glioma, breast cancer, lung cancer, ovarian cancer, and melanoma." (PMID 32411609, 2020). "Consistent with the previous report using MTHFD2 knockdown breast cancer cells, glutamate (Gln), glutamic acid (Glu), and alanine, which are metabolites in glutaminolysis, were greatly accumulated in both MTHFD2 knockdown H322 and A549 cells." (PMID 30532069, 2019). "MTHFD2 expression was also enhanced in breast cancer, as previously reported, but was more enhanced in colorectal cancer and lung cancer." (PMID 30582043, 2018). "MTHFD2 by RNAi impairs proliferation in a variety of cancer cell lines, independent of the tissue of origin, and decreases invasion and migration in breast cancer cell lines." (PMID 28210221, 2017). "MTHFD2 mRNA and protein expression is markedly elevated in many cancers and correlated with poor survival in breast cancer." (PMID 28210221, 2017). "MTHFD2 knockdown in mesenchymal type breast cancer cells induced changes indicating a switch towards more epithelial phenotype." (PMID 23295955, 2013). "This indicated that in addition to decreasing vimentin expression these pharmacological agents also downregulated MTHFD2 expression, which further validated our results on the connection between vimentin and MTHFD2 in breast cancer cells." (PMID 23295955, 2013). "Based on these results and the fact that EPHB4 had already been described as a target for breast cancer treatment, MTHFD2 was chosen for more detailed functional studies." (PMID 23295955, 2013). "The results suggested that MTHFD2 mRNA is overexpressed in breast cancer samples compared to normal breast tissues." (PMID 23295955, 2013). "It has been shown that MTHFD2 knockdown reduces cancer stem cell properties of bone metastatic breast cancer cells." (PMID 26237148, 2013). "Vimentin and TGF-β regulates MTHFD2 (methylenetetrahydrofolate dehydrogenase 2) expression in metastatic breast cancer cells." (PMID 26237148, 2013). "Analysis of MTHFD2 expression showed overexpression in breast cancer samples compared to normal breast tissues." (PMID 23295955, 2013). "Validation of MTHFD2 mRNA expression in eight different types of human normal and malignant tissues confirmed overexpression specifically in breast cancer samples." (PMID 23295955, 2013). "Our results suggest that mitochondrial enzyme MTHFD2 has a potential role in breast cancer progression." (PMID 23295955, 2013). "Instead, MTHFD2 was identified as a critical regulator of breast cancer cell migration and invasion." (PMID 23295955, 2013). "AMPK indirectly downregulates expression of the 1C metabolism enzymes, MTHFD1, MTHFD1L and MTHFD2 in breast cancer, raising the possibility that AMPK activators may sensitize cancers to anti-folate therapy." (PMID 38698089, 2024). "We confirmed MTHFD2 expression levels to be markedly up-regulated in breast cancer cells." (PMID 36726381, 2023). "The result determined that PD-L1 expression levels were positively correlated with the condition of MTHFD2 expression in breast cancer, which meant that PD-L1 inhibitors may be a promising therapeutic approach in breast cancer patients with MTHFD2 expression." (PMID 36726381, 2023).
breast carcinoma (continued). "This also confirmed the predictive value of MTHFD2 in breast cancer." (PMID 36726381, 2023). "Also, SIRT4 senses folate availability and controls MTHFD2 protein stability through regulating K50 acetylation, leading to the suppression of breast cancer cell proliferation." (PMID 37507016, 2023). "Interestingly, markedly elevated expression of MTHFD2 was identified in many cancers and correlates with poor survival in breast cancer patients." (PMID 37628752, 2023). "Interestingly, the lncRNA taurine upregulated gene 1 (TUG1) was found to negatively regulate miR-9 expression but positively regulate the expression of MTHFD2 in breast cancer cells." (PMID 37147729, 2023). "Knockdown of MTHFD2 in breast cancer cells reduced tumor growth and affected many important metabolic pathways, indicating that MTHFD2 might be a central metabolic enzyme in cancer cells." (PMID 35693982, 2022). "Increasing evidence suggests that MTHFD2 is overexpressed and predicts poor prognosis and promotes cancer cell proliferation and metastasis in certain types of malignancies, including colorectal cancer, breast cancer, and head and neck squamous cell cancer." (PMID 35135596, 2022). "In breast cancer, MTHFD2 is identified as a target of miR‐9 that inhibits cell proliferation." (PMID 34121323, 2021). "For instance, in breast cancer, MTHFD2 knockdown suppressed cell migration and invasion." (PMID 32411609, 2020). "Moreover, previous studies have not only indicated a significant correlation between MTHFD2 expression and cancer proliferation, but also MTHFD2-mediated regulation of cell motility and invasion in breast cancer." (PMID 32759461, 2020). "Moreover, the upregulated levels of MTHFD2 mRNA under low oxygen tension had been reported in breast cancer, which corresponds to our data at protein level." (PMID 32759461, 2020). "The importance of MTHFD2 has mainly been reported in breast cancer." (PMID 30582043, 2018). "MTHFD2 is highly expressed in colorectal, lung, and breast cancers compared with other cancers." (PMID 30582043, 2018). "MTHFD2 (methylenetetrahydrofolate dehydrogenase (NADP+ dependent) 2) is a source of carbon units for purine synthesis in rapidly growing cancer cells and has been associated with poor prognosis in patients with breast cancer." (PMID 29854292, 2018). "Importantly, MTHFD2 mRNA levels were elevated also in clinical breast cancer samples in comparison to normal breast tissues." (PMID 23295955, 2013). "Mitochondrial enzyme MTHFD2 has a potential role in breast cancer progression and bone metastasis." (PMID 26237148, 2013). "Importantly, MTHFD2 mRNA was overexpressed (p<0.005) in clinical breast cancer samples compared to normal breast tissues." (PMID 23295955, 2013). "Further in silico and in vitro validation in cultured breast cancer cells as well as in clinical breast cancer samples, indicated one of these genes, MTHFD2 (methylenetetrahydrofolate dehydrogenase 2), as a potential drug target to block breast cancer cell migration and invasion." (PMID 23295955, 2013). "Since TGF-β has been implicated in regulation of vimentin and promoting cell migration, we studied whether stimulation of metastatic breast cancer cells with TGF-β affects MTHFD2 expression." (PMID 23295955, 2013). "In addition to breast cancer, elevated MTHFD2 levels were detected also in colon cancer, kidney cancer and liver cancer samples." (PMID 23295955, 2013). "Moreover, MTHFD2 knockdown reduced cancer stem cell properties of bone metastatic breast cancer cells." (PMID 23295955, 2013). "Furthermore, repression of MTHFD2 decreased the invasion and migration of breast cancer cell lines." (PMID 35135596, 2022). "Additionally, a recent study demonstrated that SIRT4 deacetylates methylenetetrahydrofolate dehydrogenase/methylenetetrahydrofolate cyclohydrolase 2 (MTHFD2), a vital bifunctional enzyme in folate metabolism, to remodel folate metabolism against breast cancer cells." (PMID 36291902, 2022).